IL6 (interleukin 6)
Diseases named in the same sentence as IL6 in open-access papers (continued):
Sharing a sentence is not in itself a finding about the gene and the disease.
infection (continued). "In addition to CXCLi2, IL6 mRNA expression has been shown to increase following infection with S. Enteritidis." (PMID 29322049, 2017). "All infected mice could secrete IL-6 and TNF-α at 1 day post infection, while the uninfected mice secrete minimal level of IL-6 and TNF-α." (PMID 28468643, 2017). "Microglial cells could be rapidly activated in response to infection, inflammation, or brain injury, and thus lead to the releases of various inflammatory mediators, including IL-1β, IL-6, TNF-α, nitric oxide, reactive oxygen species, and prostaglandin E2." (PMID 28804270, 2017). "In contrast, TgPrx1 may induce hyperinflammation during the acute stage of infection because triggering the production of proinflammatory cytokines, such as Il-6 and IL-12p40, by macrophages." (PMID 28448521, 2017). "IL-6, added 2 h after infection, strongly inhibited the mycobactericidal activity of these cells." (PMID 28262681, 2017). "However, after CLP treatment elevated IL-6 levels were still detectable later in the course of infection, at 72 h, when IL-6 concentrations were still approximately 5000% higher in comparison to control mice." (PMID 28836970, 2017). "The stress response to infection may also play a role in dysglycemia, a situation mediated by the effect of interleukin-1 (IL-1), interleukin-6 (IL-6), and TNF-alpha." (PMID 29270319, 2017). "IL-6 is nonetheless also important for the development of adaptive immunity and its upregulation could help combat the infection." (PMID 28662714, 2017). "Our most recent work showed that lack of HRF causes an IL-6 increase, which boosts T and B cell responses to resolve infection via opsonized parasite-mediated phagocytosis giving rise ultimately to a cross-stage, cross-species and lasting immunity." (PMID 28831137, 2017). "During inflammation and infection, IL-6 directly regulates hepcidin expression." (PMID 28672025, 2017). "IL-6 is significantly upregulated in our model due to infection." (PMID 29348965, 2017). "Also, the levels of IL-17 and IL-6 are significantly increased in the pulmonary homogenate and serum at 16 h post-infection." (PMID 28676843, 2017). "In addition, the immune related genes RIG-1, IFN-β, IFN-γ, IL-1β and IL-6 were differentially regulated by CH60 or H strain infection in the lung (P<0.001 or P<0.01)." (PMID 28614378, 2017). "Here we assessed the levels of IL-6 expression and found that at 48 hpi, IL-6 transcripts were the sole among those tested that were differentially expressed between infections with WT and PbNK65-hrfΔ parasites, being increased six-fold in PbNK65-hrfΔ-infected liver samples." (PMID 28831137, 2017). "Hence, large intestinal IL-6 secretion as well as TNF and IL-18 mRNA levels were higher in NOD2−/− as compared to WT mice upon pathogenic infection, whereas C. jejuni induced colonic IL-22 down-regulation occurred in WT mice only." (PMID 28127403, 2017). "IL-6, IL-8, and IL-10 circulating levels were shown to be higher in cases of infection." (PMID 28148470, 2017). "IL-6 is an anti-inflammatory cytokine and a mediator of infection response." (PMID 28473693, 2017). "Indeed, while RSV induces IL-6 rapidly in vitro and in vivo in both in mouse models and humans, experimental human challenge infections find that it takes up to a week to see peak symptoms." (PMID 28953978, 2017). "Our data suggest that IL-6-production by bone marrow-derived macrophages (BMDMs) is important to promote the IL-17A production and consequent induction of a protective immune response and granuloma formation during P. brasiliensis experimental infection." (PMID 28871251, 2017). "To further clarify the timing of this effect, we measured viable intracellular BCG in cells treated before and/or after infection with IL-6; we observed that either pre-, post- or pre- and postinfection IL-6 caused a significant increase in viable intracellular BCG at 24 and 48 h." (PMID 28262681, 2017).
infection (continued). ", and both also had the greatest decrease between explantation and reimplantation demonstrating infection resolution (12.4-fold decrease for IL-1β; 11.2-fold decrease for IL-6), implicating IL-1β and IL-6 as potentially the most applicable for usage in diagnosis/prognosis of PJI." (PMID 28487810, 2017). "Depletion of IL-6 in the early stages of infection resulted in enhanced disease characterized by an influx of IFN-γ secreting virus specific T cells into the lungs and airways, dysregulation of regulatory T cell responses and reduced production of the immune-regulatory cytokines IL-10 and IL-27." (PMID 28953978, 2017). "Furthermore, blocking of TLR2-mediated signalling by the use of neutralising antibodies significantly reduced IL-6 expression after infection of A549 cells." (PMID 28195157, 2017). "However, infection with the miR-US5-1/miR-UL112-3p mutant virus still enhanced IL-6 and CCL5 levels above that observed with WT infection." (PMID 28270578, 2017). "Our findings in the present study are consistent with earlier observations that in healthy keratinocytes, IL-6 is only minimally expressed, but at sites of infection, IL-6 overexpression is stimulated by various other cytokines, including IL-1, TNF-α, and INF-γ." (PMID 29152103, 2017). "We demonstrate that aprepitant treatment attenuates B. burgdorferi-induced elevations in CCL2, CXCL13, IL-17A, and IL-6 gene expression in dorsal root ganglia, spinal cord, and/or cerebrospinal fluid of rhesus macaques at 2 to 4 weeks following intrathecal infection." (PMID 28202084, 2017). "EV-A71 infection transiently increased serum and brain IL-6 protein levels in mice." (PMID 29233145, 2017). "Furthermore, infection induced a significant increase of IL-6 and TNF-α cytokine serum levels in DM mice." (PMID 29091912, 2017). "During lytic infection, increased pro‐inflammatory cytokines IL‐6 and TNF‐α and decreased anti‐inflammatory cytokine IL‐5 may exacerbate UC." (PMID 29226079, 2017). "However, there was a marked increase in the amount of Il10 mRNA 5 days after infection in both caecum and colon, whereas mRNA levels of the pro-inflammatory cytokines IL-6 and TNFα were unchanged or moderately increased, respectively." (PMID 29241040, 2017). "Based on these results we hypothesised that the synergistic hyper-activation of MAPK p38 and to a lesser extent of MAPKs ERK1/2 and JNK might be the reason for the hyper-induction of IL-6 after super-infection." (PMID 28195157, 2017). "Interestingly, the significance in differential modulation of IP-10 and IL-6 depended on which virus mono-infection they were compared to." (PMID 28644900, 2017). "We next evaluated the role of IL-6 in Th17 differentiation during Pb18 infection." (PMID 28871251, 2017). "IL-6, a cytokine mainly produced by activated monocytes, with pleiotropic action affecting the functions of a variety of immune cells, is up-regulated during primary and secondary responses, and declines after the third infection." (PMID 28662714, 2017). "The difference between SIRS-N and SIRS-P patients was particularly pronounced for IL6 (32.7 vs. 108.7 pg/mL, p<0.0001), consistent with previous studies which have highlighted the role of IL6 as an early marker of infection and severity particularly in complicated S. aureus bloodstream infection." (PMID 31058274, 2017). "Thus, IL-1β is an important mediator in infection that stimulates intrinsic, innate and adaptive immune pathways as well as IL-6, which contributes to host defense through the stimulation of acute phase responses, hematopoiesis and immune reactions." (PMID 28737707, 2017). "Bender confirmed that this “old” marker of infection was almost as efficient as interleukin-6." (PMID 28182674, 2017). "Furthermore, CC16 modulates lung inflammatory responses to infection, injury, and allergen challenge by downregulating pro-inflammatory cytokines including IFNγ, IL-1, IL-6 and TNFα." (PMID 28380043, 2017).
infection (continued). "In addition, the TLR3 and IL6 mRNA levels were increased in HDAC1-depleted cells infection with IAV." (PMID 29312300, 2017). "In parallel with significantly elevated plasma levels of IL-17A, IL-6 as the major activating cytokine of Th17 cells also revealed significantly increased plasma levels in patients with a fungal colonization, respectively infection." (PMID 28820494, 2017). "Moreover, when categorizing patients into survivors and fatalities the IL-6 levels in fatal cases of ANDV infection were significantly higher compared to survivor or control patients." (PMID 28708900, 2017). "IL-4 and IL-6 were undetectable, but high cytokine levels were detected ≥10 days after infection." (PMID 29312230, 2017). "Further experiments using the human epithelial cell line A549 verified synergistically elevated IL-6 mRNA levels at different time points upon super-infection with IV H1N1(M), H7N7, FluB, H3N2 or H1N1 and the S. aureus strains 6850, SH1000 or MRSA USA300 compared to single pathogen-infected cells." (PMID 28195157, 2017). "A CSF pro-inflammatory response consists of an interplay of Th1 (IFN-γ and IL‐6), Th2 (IL‐4 and IL‐10) and Th17 cytokines (IL‐17A) and has been shown to be highly predictive of increased macrophage activation, rapid clearance of infection and consequently better survival in patients with CM." (PMID 28486489, 2017). "In this work, NZ2114 clearly reduced the levels of TNF-α, and IL-6 compared to the infection group." (PMID 28220445, 2017). "During CMV lytic infection, pro‐inflammatory cytokines IL‐6 and TNF‐α increased remarkably and anti‐inflammatory cytokine IL‐5 decreased, which may exacerbate UC." (PMID 29226079, 2017). "Serum IL-6 levels increase with trauma, infection, and surgery." (PMID 28473693, 2017). "In our study, the plasma levels of IL-18, IL-6, and IL-1ß were associated with infection-cause mortality but not CV-cause mortality." (PMID 28474577, 2017). "IL-6 has been found to be necessary for the clearance of Giardia in a mouse infection model." (PMID 28979269, 2017). "Whilst TRAP might indirectly influence systemic inflammation responses through a predisposition to infection, our findings are consistent with a positive and direct association between NO2 exposure and systemic IL-6 concentrations at a population level." (PMID 28481326, 2017). "Similarly, we found that P. brasiliensis experimental infection induced IL-6 synthesis even in the early infection, and this cytokine is essential to induce a Th17 immune profile." (PMID 28871251, 2017). "Importantly we found that IL-6 produced early after infection limited disease severity, but that IL-6 signalling occurring at the peak of disease had little, or limited effect on the outcome of infection." (PMID 28953978, 2017). "Similar results were obtained when mice treated between days -1 and 3 p.i. with αIL-6 were infected with mouse adapted H1N1 IAV PR8 (strain A/Puerto Rico/8/1934 H1N1), with IL-6 depleted mice showing delayed recovery from infection and reduced IL-6, IL-10 and IL-27 in the airways at day 10 p.i.." (PMID 28953978, 2017). "However, in IL-6−/− mice, EV-A71 infection decreased the numbers of all three types of lymphocytes with a significant difference found in the number of CD19+ B cells (P < 0.05)." (PMID 29233145, 2017). "Only gut epithelial cells specifically reacted to NMI infection with a significant upregulation of IL-1β, lung epithelial cells with a specific downregulation of IL-6 whereas infection with NMII resulted in a distinct up-regulation of TNF-α in lung epithelial cells." (PMID 28403908, 2017). "Moreover, IL-6 is secreted by macrophages, T cells and endothelial cells to stimulate immune response during infection leading to synthesis of a variety of inflammatory mediators including neutrophils." (PMID 28196097, 2017).
infection (continued). "Furthermore, we previously showed that BeWo cells treated with MIF or IL-6 recombinant cytokines significantly reduced the T. gondii proliferation, evidencing the important role of these mediators in the control of infection during a pregnancy." (PMID 28798905, 2017). "Due to infection, IL-6 and TNF-α significantly increased at 24 hours." (PMID 29348965, 2017). "Additionally, we also measured IL-6 protein release at 6 h post infection, the earliest time point to observe detectable amount of the cytokine." (PMID 27597997, 2016). "Furthermore, both the baseline and infection‐induced levels of IL‐6 and IL‐8 secretion were higher in the HNE cells obtained from the allergic subjects than in those obtained from the non‐allergic subjects." (PMID 27957326, 2016). "The antigen distribution of TMUV and GPV during infection in geese was coincident with the CD8+ T cell distribution, which was also associated with the high production of IFNγ and proinflammatory cytokine (IL1β and IL6) in virus-preferable tissues." (PMID 27150912, 2016). "However, significant increases in the transcription of goose IFNα, IFNγ, IL1β, and IL6 were all observed after infection with these two types of virus (TMUV and GPV) (P < 0.01; P < 0.01; P < 0.01; P < 0.01)." (PMID 27150912, 2016). "As in infection-induced inflammation, the endothelial cells may secrete increased amounts of IL-6, which can exaggerate inflammation through trans-signaling mechanisms." (PMID 27220674, 2016). "Infection with a high dose of the intracellular parasitic protozoan Leishmania major induces a sustained hyperalgesia in susceptible BALB/c mice accompanied by up-regulation of the pro-inflammatory cytokines IL-1β and IL-6." (PMID 26913003, 2016). "However, when epithelial cells were infected with a high dose of the rim101Δ/Δ mutant, IL-6 and IL-1⍺ were expressed ~8–9 hours post-infection." (PMID 27088599, 2016). "Furthermore, cytokine levels from vaginal washes of M28 GAS infected Rag1−/− and WT mice demonstrated that the Rag1−/− mice produced greater quantities of IL-1β, IL-6, and TNFα at 14, 21, and 28 days post-infection compared to WT mice." (PMID 27241677, 2016). "However, the production of IL-6, TNFα and IL-10 in response to infection with F. tularensis LVS, S. aureus or P. aeruginosa was similar between WT (C57BL/6N) and Nlrp12−/− BMDM." (PMID 27779193, 2016). "In future, the determination of IL-6 and IL-10 serum levels may be offered by routine laboratory as one more marker to evaluate the severity of infection disease at the diagnosis." (PMID 27905908, 2016). "IL6 regulates the recruitment of leukocytes during infection and may contribute to the higher neutrophil influx in cPLA2α−/− mice." (PMID 27501951, 2016). "Infection with WT K. pneumoniae induced significantly more IL-6 and CXCL2 than infection with the entB ybtS mutant, consistent with the siderophore-dependent effects observed and more IL-1β, which may be attributable to higher bacterial density." (PMID 27624128, 2016). "Notably, however, transcripts for the hemopoietins stem cell factor (SCF, also known as Kit-ligand or Steel factor), granulocyte colony-stimulating factor (G-CSF), and interleukin-6 (IL-6) were significantly reduced upon infection of BM stroma." (PMID 27540380, 2016). "LF82 infection of RWPE-1 cells induces significantly higher release of IL-6 and IL-8 than EC73." (PMID 27600504, 2016). "However, bladder macrophages exhibited increased expression of pro‐inflammatory cytokines that can promote iron retention, as evidenced by increased expression of IL‐6 and IL‐1β upon infection." (PMID 27980776, 2016). "Moreover, while the extent of upregulation of IL6 by infection remained similar in both breeds (~6.8 fold), overexpression of both IL10 and IL13 mRNA molecules was more profound in the resistant breed (CHB) than in CS." (PMID 27197554, 2016).
infection (continued). "In the initial phases, infection with the AA43 and AA44 CF-adapted variants yielded lower recruitment of innate immune cells, including neutrophil and macrophage, and less MIP-2, KC, MIP-1α, IL-6, MCP-1 and TNF-α cytokines/chemokines production than AA2." (PMID 26883959, 2016). "During SchuS4 infection, serum levels of IL-6 and G-CSF were higher while IFNγ levels were reduced." (PMID 27015566, 2016). "In our hands, infection with influenza B virus only induced modest IL-6 release." (PMID 27259950, 2016). "Interleukin-6 (IL-6), a pro-inflammatory and anti-inflammatory cytokine, is secreted by T cells and macrophages to stimulate immune response, and plays important roles in resistance against infection and bacterium." (PMID 27711227, 2016). "In fact the persistent immune activation makes CD4 T cells more susceptible to infection and causes a vicious cycle increasing the production of soluble inflammatory markers such as IFN-γ, inflammatory cytokines (i.e. IL-6) and indoleamine 2,3-dioxygenase (IDO)." (PMID 27127532, 2016). "A comparison of the host responses in the lung, brain, and spleen suggested that the differences in viral replication efficiency were related to the host cytokine response at the early phase of infection, especially variations in the proinflammatory cytokine IL-6." (PMID 27078641, 2016). "WT PR8 infection induced higher levels of proinflammatory cytokines, such as TNF-α, CXCL12, and interleukin 6 (IL-6), than infection with the segment 8 reassortant viruses, while the profiles in O175A- and O265B-infected mice were more similar to each other than to the profile in PR8-infected mice." (PMID 27489273, 2016). "To evaluate the infection in the staphylococcal osteomyelitis model, we measured the serum interleukin-6 (IL-6) and C-reactive protein (CRP) in retro-orbital blood samples collected before surgery and on post-surgical days 1, 3, 7, and 14 from mice in the control and ionic-silver groups (n = 3, 3)." (PMID 26984477, 2016). "Moreover, blood levels of IL-6 at days 1, 2 and 3 and IL-12p40 at days 2, 3 and 7 were significantly up regulated following infection with W. chondrophila." (PMID 26950066, 2016). "Our model consists of a number of non-linear ordinary differential equations describing lung dynamics of pneumococcal population, the inflammatory cytokine IL-6, neutrophils and macrophages fighting the infection and destruction of alveolar tissue due to pneumococcus." (PMID 27196107, 2016). "The pattern of the major cytokines associated to infection was similar in BALF, although in serum of PSGL-1−/− mice there were significant increased levels of IL-5, IL-6, and IFN-γ (P <0.05) which is compatible with the higher bacterial levels found in the blood of these mice." (PMID 26975045, 2016). "In contrast, M28 GAS elicited significant cytokine increases in TNF-α, IL-17A, IL-6, IL-1β, and IL-22, as early as 3 to 7 days post-infection in the estradiol pulse model, and a significant cellular infiltrate in the lumen was observed in colonized WT mice compared to non-infected or IL-17A−/− mice." (PMID 27241677, 2016). "At 48 h post-infection, IL-6 expression was analyzed by real-time RT-PCR and ELISA." (PMID 27852059, 2016). "Aldwell and the coworkers, by contrast, observed enhanced expression of genes for the proinflammatory cytokines IL-1β, IL-6, and TNFα only after in vitro infection of bovine macrophages in bronchoalveolar fluid with pathogenic M. bovis, but not with attenuated BCG-mycobacteria." (PMID 27066505, 2016). "In cells pre-exposed to P. aeruginosa before RSV-infection, we only detected a small, yet statistically significant synergistic effect on IL-6 production 24 h after infection (mean increase over additive effect 8 % ± 2 %, p = 0.002), but not at the later time points." (PMID 27259950, 2016).